CD4 (CD4 molecule)
Diseases named in the same sentence as CD4 in open-access papers (continued):
Sharing a sentence is not in itself a finding about the gene and the disease.
leprosy (continued). "In both types of reactions, CD4+CD25+ Treg cells showed significant reduction in MFI of FOXP3 in antigen stimulated PBMC of (p<0.02, p<0.003) though qPCR showed an increase in its expression as compared to stable non reactive lepromatous leprosy patients." (PMID 27035913, 2016). "This study shows the recovery of the cell mediated response by CD4+ T cells by inhibiting the suppressive cytokines, IL-10 and TGF-β and also by blocking of the Programmed Death-1 pathway in cells isolated from lepromatous leprosy patients." (PMID 26751584, 2016). "It has also been observed in gingival tissue biopsies from lesions of patients with leprosy, saliva, and GCF; it is secreted by CD4+ T cells, CD8+ lymphocytes, peripheral blood mononuclear cells, and natural killer (NK) cells, which are also related to periodontal bone loss." (PMID 26339136, 2015). "For example, the recent molecular analysis of FoxP3 in CD4+CD25+ T cells nuclei has revealed that the FoxP3 interaction with histone deacetylases drives the immune suppression by CD4+ CD25+ Tregs in BL/LL unlike in other forms of leprosy." (PMID 24722473, 2014). "Differences between the two clinical types of leprosy were only observed with TGF-β producing CD4+T cells which had CD25+FOXP3+ phenotype (p<0.002) and not with FOXP3+ cells alone or where CD25 was absent." (PMID 24454972, 2014). "In this study, we evaluated for the first time the frequency of CD4+ and CD8+ Treg in leprosy patients and HHC, in both cases under 15 years old, and their relation with the clinical forms of the disease, to shed light on their role in the pathogenesis of the disease in this age group." (PMID 24244424, 2013). "The location and distribution of CD4 and CD8 cells in leprosy lesions have been well described; tuberculoid lesions have abundant T cells in the granuloma of a CD4 lineage, fewer T cells are found in the LL skin lesions and they have a higher proportion of CD8 cells." (PMID 22180790, 2011). "In leprosy, two patterns of in situ localization of T lymphocytes subsets have been described: in tuberculoid lesions CD8+ (OKT8+) cells are found around the granulomata, and CD4+ (OKT4+) cells are distributed throughout the granuloma." (PMID 22029431, 2011). "In addition, we examined whether PD-1 was expressed on CD4+ and CD8+ T cells in the peripheral blood of leprosy patients and found that their frequencies of PD-1-expressing CD4+ and CD8+ T cells were significantly higher compared to healthy controls." (PMID 37153623, 2023). "TGF-β was seen in CD25+ cells of the CD4+ but not that of CD8+ T cell lineage in leprosy patients." (PMID 24454972, 2014). "CD4+CD25+FOXP3+ T cells (Tregs) were increased in unstimulated basal cultures (p<0.0003) and showed further increase in in vitro antigen but not mitogen (phytohemaglutinin) stimulated PBMC (iTreg) in lepromatous as compared to tuberculoid leprosy patients (p<0.002)." (PMID 24454972, 2014). "Interestingly, these animals also exhibited CD4+ T cell infiltration into the nerves, a phenomenon which has not been previously reported in leprosy mouse models." (PMID 25210773, 2014). "The pathogenesis of IRIS in leprosy has not yet been clearly defined, but the re-establishment of CD4+ and CD8+ T lymphocytes after HAART may explain their development." (PMID 22205964, 2011). "Another exciting aspect that has been demonstrated is that, in the emergence of leprosy, clinical forms and cure with standard polychemotherapy (MDT) are not related to CD4 levels or viral load." (PMID 34748560, 2021). "Several studies have reported increased percentage of CD4+ T-cells and reduced CD8+ T-cells with an increased CD4+/CD8+ ratio in patients with ENL compared to patients with non-reactional lepromatous leprosy." (PMID 29028793, 2017). "Taken together, our studies show an increase in TGF-β+ CD4+ CD25+ FOXP3+ T cells both in dermal lesions and in in vitro induced antigen but not mitogen stimulated PBMC (iTreg) of lepromatous leprosy patients." (PMID 24454972, 2014).
leprosy (continued). "In the sample studied, there was a positive correlation between FOXP3+ cell density and viral load, negative correlation with blood CD4+ (not statistically significant), significant positive correlation in CD8 count in patients with leprosy reaction, and positive relationship in patients with IRIS." (PMID 34748560, 2021). "Unlike IL-17, IL-21 was present in both CD4+ and CD8+ T cells in the two clinical types of leprosy." (PMID 23936569, 2013). "However, CD4+IL23R+ cells were detected without any difference between T1R and NR leprosy patients." (PMID 32934336, 2020).
non-Hodgkin lymphoma (56 papers, 2005 to 2026). Distinct from Hodgkin lymphoma both morphologically and biologically, non-Hodgkin lymphoma (NHL) is characterized by the absence of Reed-Sternberg cells, can occur at any age, and usually presents as a localized or generalized lymphadenopathy associated with fever and weight loss. "Having a higher number of infused CD4+PD-1− was associated with better progression-free survival post auto-HSCT in patients with non-Hodgkin lymphoma in one study." (PMID 39329729, 2024). "CTSS inhibition caused antigen diversification in non-Hodgkin lymphoma that switched immunity by promoting CD8+ T cell polyclonal expansion and suppressing CD4+ T cells." (PMID 40707961, 2025). "In HIV-positive individuals at risk for developing non-Hodgkin lymphoma (pre-NHL), CD8+PD-1+CD27+CXCR4− T-cells positively correlate with CD4+FoxP3+PD-1+ T-cells expressing CD27, CD28, ICOS, and CD71." (PMID 41148820, 2025). "Burkitt lymphoma accounts for 10–35% of AIDS-defining lymphoma in people with HIV, making it the second most common subtype of non-Hodgkin’s lymphoma occurring in HIV-positive patients with a relatively high CD4 cell count." (PMID 38611075, 2024). "Karpas 299 (K299) cells were originally established from a high-grade non-Hodgkin’s lymphoma and had some T cell properties, including the expression of CD4 and CD5." (PMID 38534788, 2024). "However, with inadequate treatment/treatment resistance, 25–40% may develop a malignancy, with 10% of these being non-Hodgkin lymphoma (NHL) Key risk factors for NHL in HIV infected individuals include a CD4 count below 100 and HIV RNA viral levels exceeding 1000 copies." (PMID 37964357, 2023). "Peripheral T cell lymphomas (PTCLs) are a type of non-lymphoma Hodgkin’s (NHL) that comes up from mature T cells that express CD4 antigen widely and uniformly." (PMID 34215336, 2021). "Cutaneous T-cell lymphoma is a group of incurable extranodal non-Hodgkin lymphomas that develop from the skin-homing CD4+ T cell." (PMID 30518749, 2018). "Non-Hodgkin lymphoma was found in patients in both CD4 count groups." (PMID 35042469, 2022). "Also, the COHERE study showed that during HAART higher CD4+ cell counts are protective for the development of non-Hodgkin lymphoma." (PMID 22474480, 2012). "HS is diagnosed using positive immunohistochemistry for histiocytic markers, such as CD68, CD4, CD163, or lysozyme, and can present in an isolated form or be associated with other hematologic malignancies, such as non-Hodgkin lymphoma (NHL) or acute leukemia." (PMID 40066099, 2025). "In the case of hematological malignancies, patients with non-Hodgkin’s lymphoma (NHL) exhibit an increase in CD14+ HLA-DRlow-expressing monocytes, which possess immunosuppressive properties, along with elevated levels of CD4+ CD25+ Tregs." (PMID 41303751, 2025). "Non-Hodgkin’s lymphoma (NHL) is the most frequent pathological subtype in patients with advanced HIV infection, a low CD4+ count (<100 cells/μL), and a high HIV load." (PMID 30926889, 2019). "PCNSL is a non-Hodgkin lymphoma that is intricately related to EBV infection, an important consideration in severely immunosuppressed patients, and it occurs in 2–6% of HIV patients with advanced disease (CD4 < 100 cells/uL)." (PMID 36769419, 2023). "A previous study found the high ratio of CD3+/HLA-DR+ T cells, both on CD4+ helper and CD8+ cytotoxic T cells after chemotherapy, may predict the danger of relapse in patients with non-Hodgkin's lymphoma." (PMID 36035394, 2022). "Indeed, in patients with non-Hodgkin’s lymphoma, naive and central memory CD4+ CAR-T cells from patients exhibit higher antitumor activity than effector memory CD4+ CAR-T cells when transferred to an animal model." (PMID 33450845, 2021).
non-Hodgkin lymphoma (continued). "One case of primary non-hodgkin's lymphoma of liver (diffuse large T-cell type) showed large polygonal cells with a deeply eosinophilic cytoplasm and large nuclei and immunohistochemical analysis of it showed the lesion to be homogeneously positive for CD3, CD4, CD8, and CD43." (PMID 21660276, 2011). "Neither CD4 nor CD8 T cells killed RKO, an HLA-I mismatched human colorectal tumor cell line, or Raji, an HLA-II+ mismatched non-Hodgkin lymphoma cell line, confirming that the killing was HT-29 specific." (PMID 37185301, 2023).
sexually transmitted infections (56 papers, 2011 to 2025). "Protection against other sexually transmitted infections such as Chlamydia is also associated to presence of effective CD4+ TRM in the genital mucosa." (PMID 31628331, 2019). "Higher background SFU was associated with history of sexually transmitted infections (P = 0.03), and illness in the past 3 months (P = 0.005), in addition to increased levels of activated CD4+ and CD8+ cells (P range = 0.008–0.03)." (PMID 29974672, 2018). "Those Women who had multiple sexual partners, a history of sexually transmitted infections, had a history of early (before age 18 years) initiation of sexual intercourse, had Baseline CD4 count Less than 200/mm3 had a significant association with a precancerous cervical lesion." (PMID 37644484, 2023). "We therefore set out to characterize and compare the expression of α4β7, α4β1 and αEβ7 integrins on systemic, cervical and rectal CD4+ and CD4negT cells isolated from a cohort of healthy Kenyan women at low risk for sexually transmitted infections (STI) (n = 45)." (PMID 29420608, 2018). "With these sexually transmitted infections, this inflammatory phenotype has been associated with an increased susceptibility to the human immunodeficiency virus (HIV) as CD4+ is the main target of the virus (29, –, 31)." (PMID 39840991, 2025). "Among PWH with severe manifestations of mpox, 90% were receiving ART prior to diagnosis, 93% had a CD4 count less than or equal to 200 copies/mm3, 28% had a co-occurring sexually transmitted infection (STI), and 23% were unstably housed." (PMID 38392862, 2024). "the study found homosexual intercourses, early examination, anti-HIV antibodies, CD4 count, and sexually transmitted infection as the main attributes of the concept." (PMID 37556698, 2023). "Among the most evident attributes in this study are homosexual intercourses (14%), early examination (12%), anti-HIV antibodies, CD4 count, and sexually transmitted infections (9%)." (PMID 37556698, 2023). "They included lower education, smoking, younger age, lower CD4 cell counts, higher nadir CD4 cell counts, number of sex partners, receptive anal intercourse, having sexual transmitted infections (STIs)." (PMID 27548632, 2016). "Logistic and Cox regression were used to identify factors associated with prevalent, incident and persistent genital warts, including HIV-1 serostatus, CD4+ count, and concurrent sexually transmitted infections." (PMID 21251265, 2011). "In this regard it is noteworthy that the antigen-specific response to certain sexually transmitted diseases (STDs) involves α4β7+ CD4+ T cells." (PMID 21284901, 2011). "Lubricant use was associated with increased frequencies of colonic CD4+, NKT, and CD4+PD-1+ T cells, while individuals who had experienced a recent sexually transmitted infection (STI) displayed higher levels of naïve CD4+ T cells in the blood compared to those without a recent STI." (PMID 41550925, 2025). "In the bivariable analyses, variables significantly associated with HR-HPV infections based on P<0.20 were recent CD4+ cell count ≤560 cells/μL, first pregnancy before age 23 years, nulliparity, being economically unengaged, and having previous treatment for sexually transmitted infections." (PMID 39070626, 2024). "This study confirms that having a history of sexually transmitted infection, two or more lifetime sexual Partners, the initiation of sexual intercourse before the age of 18 years, and Baseline CD4 count < 200 cells/mm3 were determinants for precancerous cervical lesions." (PMID 37644484, 2023). "This study revealed that having two or more sexual partners, having a history of a sexually transmitted infection, beginning a relationship before turning 18 years old, and having a baseline CD4 count below 200 cells/mm3 were indicators of precancerous cervical lesions." (PMID 37644484, 2023).
sexually transmitted infections (continued). "However, as long as more than 50% of our patients showed a CD4+ T-cell count nadir <200 cell/mm3, we can hypothesize a lack of attention from both clinicians and prevention strategies in this population, which may perceive a lower risk of sexually transmitted diseases in this population." (PMID 31622347, 2019). "Sexually transmitted infection screening showed positive HIV‐1 serology with a viral load of 609,656 copies/mL, a CD4+ count of 107/mm3, and a CD4/CD8 ratio of 0.26." (PMID 39513741, 2024). "Trained community health-workers provided same-day result HIV testing and sexually transmitted infection (STI) screening, as well as CD4 testing and linkage to care for HIV-infected participants." (PMID 28953320, 2017). "A quarter of the subjects had sexually transmitted diseases in addition to HIV, and 80.8% of the individuals had CD4 counts equal to or above 350 cells/μl." (PMID 25035709, 2014). "In vivo visualization studies of pathogen-specific CD4 T cell responses have typically involved adoptive transfer of monoclonal TCR transgenic T cells and have rarely focused on sexually transmitted infections." (PMID 24204262, 2013). "Since the patient had a positive Treponema pallidum latex agglutination result before admission, further examinations for sexually transmitted disease were performed, which showed that he was positive for HIV H-1 antibodies, with reduced CD4 level (<45/μL) and a CD4/CD8 ratio of 0.3." (PMID 33786101, 2021). "Indeed, the presence of a pro-inflammatory local environment, similar to that observed during sexually transmitted infections (STI), favors the establishment of HIV infection, since inflammation mediate the recruiting and activation of CD4+ target cells in FRT." (PMID 30787929, 2019). "Participants were asymptomatic adults without sexually transmitted diseases, treatment-naive people living with HIV (PLWH), with CD4+ T cell counts >200 cells/mm3 and plasma HIV-1-RNA levels >5000 and <500 000 copies/mL, randomized (1:1) to DTG + TAF/FTC or dolutegravir/lamivudine." (PMID 37545387, 2023).
herpes zoster (55 papers, 2011 to 2026). A common dermal and neurologic disorder caused by reactivation of the varicella-zoster virus that has remained dormant within dorsal root ganglia, often for decades, after the patient's initial exposure to the virus in the form of varicella (chickenpox). "The most significant risk of neurologic complications of disseminated herpes zoster is in patients with HIV whose CD4 cell count is less than 200 cells/mm3." (PMID 39055723, 2024). "The decline in VZV-specific CD4+ T-cell responses has been associated with an increased risk of herpes zoster in older adults." (PMID 38575581, 2024). "HIV-positive adults can develop herpes zoster at any CD4, but the risk increases at CD4 levels below 200 cells/mm3." (PMID 39006335, 2024). "A high incidence of herpes zoster (HZ) has been reported in HIV-infected patients with a lower CD4 count, but the risk of HZ has decreased in the cART." (PMID 37623953, 2023). "In VZV vaccination studies in bone marrow recipients, the risk of zoster reactivation inversely correlated with the frequencies of VZV-specific CD4+ T cells." (PMID 27764254, 2016). "The CD4 decline was rapidly associated with an increased incidence of herpes zoster (<500 CD4 per mm3), but further immunosuppression only marginally increased the incidence of herpes zoster." (PMID 24244647, 2013). "Additionally, HIV patients are more susceptible to herpes zoster during the phase in which absolute numbers of CD4 T cells decline, highlighting the importance of CD4 T cell responses in controlling VZV infection." (PMID 22102814, 2011). "It has been reported that the majority of patients showed specific CD4+ T cells after vaccination with recombinant zoster vaccine under upadacitinib and MTX." (PMID 40635091, 2025). "CVE induced dominant CD8+ T-cell responses and measurable CD4+ T-cell responses while establishing LLPCs and memory T cells (TCMs and TRMs), indicating the potential for long-term protection against herpes zoster." (PMID 41441692, 2025). "Another strength of this study is that it examines both humoral (e.g., anti-gE, VZV-specific antibodies) and cellular (e.g., gE-specific CD4+ T-cells) immunity, since cellular immunity is considered a more reliable predictor of herpes zoster protection." (PMID 39685779, 2024). "In conclusion, we showed that the inactivated herpes zoster HZ/su vaccine was well tolerated and induced specific antibodies and polyfunctional CD4 T-cells in both patients and controls." (PMID 39265505, 2024). "Herpes zoster can occur in adults with HIV at any CD4 lymphocyte cell count, but the risk of disease is higher with CD4 counts <200 cells/mm3." (PMID 37581910, 2023). "Patients with HIV with CD4 counts under 200 μL during or after treatment for herpes zoster should be followed carefully for neurological symptoms." (PMID 37518182, 2023). "This led to some guidelines recommending PcP- and herpes zoster prophylaxis in MM patients showing CD4+-T-cell-numbers <200/μl." (PMID 37152008, 2023). "Here we assessed the functional and transcriptomic properties of peripheralblood CD4+ T cells in persons with acute herpes zoster (HZ) comparedto those with a prior history of HZ infection using multicolor flowcytometry and RNA sequencing." (PMID 36865570, 2022). "In patient #1, the ratio of CD8‐positive T lymphocytes was higher than that of CD4‐positive T lymphocytes before starting with chemotherapy, but the difference increased after the patient developed herpes zoster." (PMID 35315593, 2022). "Annual assessments were performed for efficacy against herpes zoster (HZ) from Y6 post-vaccination and for anti-gE antibody concentrations and gE-specific CD4[2+] T-cell (expressing ≥2 of 4 assessed activation markers) frequencies from Y5 post-vaccination." (PMID 34283213, 2022). "A steady decline of VZV-specific CD4+ T cells over time has been documented, which is only very transiently boosted with zoster vaccination or reactivation." (PMID 31608061, 2019).